MYBPC3 (myosin binding protein C3)
Description:
Thick filament-associated protein located in the crossbridge region of vertebrate striated muscle a bands. In vitro it binds MHC, F-actin and native thin filaments, and modifies the activity of actin-activated myosin ATPase. It may modulate muscle contraction or may play a more structural role.
Synonyms: FHC; cMyBP-C; CMD1MM; CMH4; LVNC10; MYBP-C
Tractability: PROTAC: UniProt records ubiquitination sites on it.
Gene: Protein-coding gene on chromosome 11 (47,331,406 to 47,352,702, reverse strand). Ensembl gene ENSG00000134571.
Pathways (Reactome):
Muscle contraction: Striated Muscle Contraction
Gene Ontology:
Molecular function: identical protein binding; myosin binding; myosin heavy chain binding; protein binding; structural constituent of muscle; ATPase activator activity; titin binding
Biological process: heart morphogenesis; ventricular cardiac muscle tissue morphogenesis; cardiac muscle contraction; regulation of cardiac muscle cell contraction; regulation of muscle filament sliding; regulation of striated muscle contraction; sarcomere organization
Cellular component: A band; cardiac myofibril; sarcomere; striated muscle myosin thick filament; C zone; cytosol; M band
Genetic constraint (gnomAD): Loss-of-function variants: 106 observed, 136.18 expected, observed/expected ratio (o/e) 0.78, 90% interval 0.66 to 0.92. The upper end of that interval is the gene's LOEUF score, 0.92, which puts it in group 3 of 6, group 1 being the genes least tolerant of losing a copy. Missense variants: 1,630 observed, 1,641.4 expected, observed/expected ratio (o/e) 0.99, 90% interval 0.95 to 1.03. Synonymous variants: 730 observed, 653.41 expected, observed/expected ratio (o/e) 1.12, 90% interval 1.05 to 1.19.
Gene-disease validity (ClinGen):
ClinGen rates the evidence that MYBPC3 causes each of these diseases.
hypertrophic cardiomyopathy (autosomal dominant): Definitive. A condition in which the myocardium is hypertrophied without an obvious cause.
arrhythmogenic right ventricular cardiomyopathy (autosomal dominant): Limited.
congenital heart disease (autosomal dominant): Limited. A heart disease that is present at birth.
dilated cardiomyopathy (autosomal dominant; autosomal recessive): Limited. Cardiomyopathy which is characterized by dilation and contractile dysfunction of the left and right ventricles.
Homologues: Orthologues: chimpanzee MYBPC3 (99% identical), macaque MYBPC3 (97% identical), rabbit MYBPC3 (90% identical), mouse Mybpc3 (90% identical), rat Mybpc3 (89% identical), dog MYBPC3 (89% identical), pig MYBPC3 (89% identical), guinea pig MYBPC3 (85% identical), tropical clawed frog mybpc3 (65% identical), zebrafish mybpc3 (62% identical). Paralogues in human: MYBPC2 (49% identical), MYBPC1 (45% identical), IGSF22 (22% identical), MYOM1 (20% identical), MYOM2 (20% identical), MYOM3 (19% identical), OBSL1 (18% identical), MYBPH (18% identical), FNDC3B (14% identical), FNDC3A (14% identical), MYBPHL (13% identical).
Diseases named in the same sentence as MYBPC3 in open-access papers:
MYBPC3 is named in the same sentence as 123 diseases in open-access papers, as found by Europe PMC text mining. Sharing a sentence is not in itself a finding about the gene and the disease. The quoted sentences say what the papers report.
hypertrophic cardiomyopathy (164 papers, 2008 to 2026). "The most frequently pathogenic variants in hypertrophic cardiomyopathy are MYBPC3 and MYH7, which together account for approximately 70% of cases." (PMID 41019439, 2025). "Myosin-binding protein C (MYBPC3) variants are primarily associated with hypertrophic cardiomyopathy (HCM)." (PMID 40115818, 2025). "Autosomal dominant pathogenic variants in MYBPC3 are the leading cause of familial hypertrophic cardiomyopathy (HCM)." (PMID 41292636, 2025). "Rare diseases (monogenic), such as hypertrophic cardiomyopathy (e.g., MYBPC3, MYH7 mutations), dilated cardiomyopathy (LMNA, RBM20), or inherited arrhythmias (KCNQ1, RYR2), are often caused by single, well-characterized mutations." (PMID 40465697, 2025). "Bi-allelic pathogenic variants in MYBPC3 cause a rare and lethal neonatal form of hypertrophic cardiomyopathy (HCM) that often evades detection during routine prenatal screening." (PMID 41488457, 2025). "We edited 1,137 variants into two exons of MYBPC3, where pathogenic variants are the most common cause of familial hypertrophic cardiomyopathy." (PMID 41292636, 2025). "Previous research has established a direct correlation between mutations in the MYBPC3 gene and cardiac dysfunction, resulting in hypertrophic cardiomyopathy." (PMID 40426840, 2025). "One individual was heterozygous for the MYBPC3 p.Gly531Arg pathogenic variant associated with hypertrophic cardiomyopathy (HCM), and two individuals were heterozygous for the KCNQ1 p.Arg397Trp (LP) variant implicated in long QT syndrome (LQTS)." (PMID 40970488, 2025). "In contrast, mutations in MYBPC3, the most prevalent genetic cause of hypertrophic cardiomyopathy, exhibit considerable clinical heterogeneity, ranging from asymptomatic carriers to patients with advanced heart failure and sudden cardiac death." (PMID 41010045, 2025). "Hypertrophic cardiomyopathy (HCM) is an inherited cardiomyopathy often caused by pathogenic variants in MYBPC3 and MYH7, encoding myosin‐binding protein C3 and myosin heavy chain 7, respectively." (PMID 40613316, 2025). "About half of the mutations that lead to hypertrophic cardiomyopathy (HCM) occur in the MYBPC3 gene." (PMID 39456977, 2024). "For example, pathogenic variants in MYBPC3 gene increase the risk of developing hypertrophic cardiomyopathy, a disease caused by dysfunction in the cardiac muscles which can lead to arrhythmia and sudden death." (PMID 38752549, 2024). "About 50% of mutations leading to hypertrophic cardiomyopathy occur in the MYBPC3 gene, which encodes cardiac myosin-binding protein C (cMyBP-C)." (PMID 39456977, 2024). "Mybpc3 mutations are associated with familial hypertrophic cardiomyopathy in humans, fibrosis in pigs, and hypertrophy in mice." (PMID 38533084, 2024). "Variants in the MYBPC3 gene are a frequent cause of hypertrophic cardiomyopathy (HCM) but display a large phenotypic heterogeneity." (PMID 38836037, 2024). "The second patient, the proband’s sibling, is a male infant diagnosed with hypertrophic cardiomyopathy and carries the same homozygous MYBPC3 variant." (PMID 36980931, 2023). "Pathogenic variants in MYBPC3 are one of the main causes of hypertrophic cardiomyopathy (HCM) development." (PMID 36980931, 2023). "Allelic imbalance has been observed at the protein level in hypertrophic cardiomyopathy for only a few missense mutations in MYBPC3." (PMID 37445689, 2023). "Discovered in the early 70 s, MyBP-C catapulted to great importance on the discovery of hypertrophic cardiomyopathy (HCM) resulting from mutations in MYBPC3." (PMID 37115473, 2023). "Various molecular mechanisms have been suggested as the pathogenesis underlying hypertrophic cardiomyopathy (HCM) caused by truncated variants of MYBPC3." (PMID 37445689, 2023). "Here, we established a hiPSC line with a heterozygous frameshift mutation from a patient with hypertrophic cardiomyopathy caused by an MYBPC3 mutation (Mybpc3t/+)." (PMID 37236659, 2023).
hypertrophic cardiomyopathy (continued). "It has been demonstrated that viral expression of the hypertrophic cardiomyopathy-associated sarcomere gene myosin binding protein C (MYBPC3), can lead to the replacement of the endogenous protein without overexpression." (PMID 38665939, 2023). "Intronic variants in MYBPC3 in the context of hypertrophic cardiomyopathy have also been identified and, in the last few years, have focused on one specific intronic MYBPC3 variant c.1224-52G>A (IVS13-52G>A)." (PMID 36980931, 2023). "The vast majority of the MYBPC3 variants that lead to hypertrophic cardiomyopathy are present in adult populations and have been associated with late-onset disease." (PMID 36980931, 2023). "Four patients had a diagnostic variant in MYBPC3, which is predominantly associated with hypertrophic cardiomyopathy." (PMID 37795486, 2023). "MYBPC3 mutations have previously been linked to a less super-relaxed state in patients with hypertrophic cardiomyopathy (HCM)." (PMID 37754829, 2023). "Mutations in the MYBPC3 gene encoding cardiac myosin-binding protein C (cMyBPC) are among the most common gene mutations found in hypertrophic cardiomyopathy." (PMID 37236659, 2023). "We previously showed that monoallelic DSBs selectively induced on the paternal locus of MYBPC3 gene carrying pathogenic 4 bp deletion, implicated in hypertrophic cardiomyopathy, resulted in LOH due to loss of the mutant paternal allele." (PMID 36882397, 2023). "Mutations in the MYBPC3 gene coding for MyBP-C are the most common cause of familial hypertrophic cardiomyopathy (HCM)." (PMID 35846001, 2022). "Overall, 3/4 LP variants (75%) were found in genes associated with hypertrophic cardiomyopathy (HCM) (MYBPC3 c." (PMID 36588553, 2022). "The identification and characterization of these spliceogenic MYBPC3 variants by the pioneer studies represented the first evidence that mutations in the MYBPC3 gene cause familial hypertrophic cardiomyopathy." (PMID 35508642, 2022). "Myosin-binding protein C3 A31P (MYBPC3-A31P) missense mutation is a genetic deviation associated with the development of hypertrophic cardiomyopathy (HCM) in Maine Coon cats." (PMID 35321056, 2022). "In cats, mutations in myosin binding protein C (encoded by the MYBPC3 gene) have been associated with hypertrophic cardiomyopathy (HCM)." (PMID 33561224, 2021). "Variants in MYBPC3 causing loss of function are the most common cause of hypertrophic cardiomyopathy (HCM)." (PMID 33782553, 2021). "The myosin-binding protein C (MYBPC3) c.927-2A>G founder mutation accounts for >90% of sarcomeric hypertrophic cardiomyopathy (HCM) in Iceland." (PMID 32341788, 2020). "A large number of unique MYBPC3 variants and relatively small genotyped hypertrophic cardiomyopathy cohorts have precluded detailed genotype-phenotype correlations." (PMID 32841044, 2020). "Mutations in MYBPC3 were previously associated with a lower super-relaxed state in patients with hypertrophic cardiomyopathy (HCM)." (PMID 32612638, 2020). "Patients with hypertrophic cardiomyopathy and MYBPC3 variants were identified from the Sarcomeric Human Cardiomyopathy Registry." (PMID 32841044, 2020). "Pathogenic variants in MYBPC3, encoding cardiac MyBP-C (myosin binding protein C), are the most common cause of familial hypertrophic cardiomyopathy." (PMID 32841044, 2020). "For example, correction of the MYBPC3 gene is arguably a better target for embryonic gene editing, as mutations in MYBPC3 can cause hypertrophic cardiomyopathy (HCM), a heart condition responsible for most sudden cardiac deaths in people under the age of 30." (PMID 32850447, 2020). "MYBPC3 encodes the cardiac isoform of myosin‐binding protein C. Mutations in MYBPC3 are one cause of familial hypertrophic cardiomyopathy." (PMID 31595719, 2019).
hypertrophic cardiomyopathy (continued). "A healthy medical student was given a direct-to-consumer genetic test for Christmas, and explored the raw data from this test using an online interpretation programme, finding a variant in MYBPC3 that was predicted to cause hypertrophic cardiomyopathy." (PMID 30837331, 2019). "It was used to assess the splice-altering impact of a pathogenic cryptic splice variant in the MYBPC3 intron associated with hypertrophic cardiomyopathy (ORPHA:217569)." (PMID 31783696, 2019). "Mutation in this gene (MYBPC3-Q1061X) results in hypertrophic cardiomyopathy and cardiac oxidative stress with elevated TG and branched-chain amino acid levels." (PMID 31086608, 2019). "Truncating mutations in the MYBPC3 gene that codes for cardiac MyBP-C are associated with hypertrophic cardiomyopathy and are one of the most thoroughly investigated examples of haploinsufficiency." (PMID 29997361, 2018). "The group was able to successfully edit human zygotes with a heterozygous mutation in the MYBPC3 gene causing hypertrophic cardiomyopathy." (PMID 29731778, 2018). "Previous studies showed that mutations in MYBPC3 genes are one of the most common genetic causes of hypertrophic cardiomyopathy (HCM)." (PMID 29854750, 2018). "Initial reports of successful gene editing in humans include gene editing on embryos at risk for hypertrophic cardiomyopathy caused by MYBPC3 mutation and treatment-resistant leukemia." (PMID 29487844, 2018). "The MYBPC3 variant c.1504C > T (p.Arg502Trp) is considered one of the most common pathogenic variants of hypertrophic cardiomyopathy in individuals of European descent and it was observed with an allele frequency of 0.0025%." (PMID 28166811, 2017). "In conclusion, we reported that MYBPC3 is the most commonly mutated gene among our study population with hypertrophic cardiomyopathy, almost twice that of MYH7, which was previously suggested as the most common genetic cause of familial HCM." (PMID 29121657, 2017). "Here, we report the effect of mutations in the cMyBP-C gene (MYBPC3) using samples from human patients with hypertrophic cardiomyopathy (HCM)." (PMID 28658286, 2017). "One recent example of a controversial DNA test in cats was the A31P and A74T variants in myosin-binding protein C3 (MYBPC3) for hypertrophic cardiomyopathy (HCM)." (PMID 27370326, 2016). "MYBPC3 mutations cause hypertrophic cardiomyopathy, which is frequently associated with mitral valve (MV) pathology." (PMID 26819945, 2015). "Mutations in the cardiac myosin-binding protein C gene (MYBPC3) are the most common genetic cause of hypertrophic cardiomyopathy (HCM) worldwide." (PMID 26267065, 2015). "We conclude that MYBPC3 deficiency causes hypertrophic cardiomyopathy with increased MV leaflet length and thickness despite the absence of left ventricular outflow-tract obstruction, in parallel with increased TGFβ activity." (PMID 26819945, 2015). "We also identified two SUN2 variants, encoding variants p.M50T and pV378I, in patient MD-2 who had hypertrophic cardiomyopathy and also carried a mutation in MYBPC3 (p.G148R), which encodes a myosin binding protein." (PMID 25210889, 2014). "Here, we determined how serum affected cardiomyocytes from human embryonic- (hESC) and induced pluripotent stem cells (hiPSC) and hiPSC from patients with hypertrophic cardiomyopathy linked to a mutation in the MYBPC3 gene." (PMID 24981391, 2014). "In Maine Coon (MC) cats the c.91G > C mutation in the gene MYBPC3, coding for cardiac myosin binding protein C (cMyBP-C), is associated with feline hypertrophic cardiomyopathy (fHCM)." (PMID 21306647, 2011). "Mutations in MYBPC3 can cause hypertrophic cardiomyopathy that is characterized by cardiac hypertrophy, myocyte disarray, contractile dysfunction and sudden death." (PMID 20585402, 2010). "MyBPC3 mutations are amongst the most frequent causes of hypertrophic cardiomyopathy, however, its prevalence varies between populations." (PMID 20433692, 2010).
hypertrophic cardiomyopathy (continued). "MYBPC3 mutations are the leading cause of hypertrophic cardiomyopathy." (PMID 41158753, 2026). "Earlier genetic analyses revealed crucial insights into the main genetic culprits of these disorders, such as SCN5A for Brugada syndrome, and MYH7 and MYBPC3 for hypertrophic cardiomyopathy, which have revolutionized diagnosis, risk stratification, and medical management." (PMID 41465121, 2025). "Hypertrophic cardiomyopathy (HC), affecting approximately 0.2% to 0.5% of global adult population, is often associated by loss-of-function mutations in myosin binding protein C3 (MYBPC3)." (PMID 41179895, 2025). "Moreover, the cardiac myosin-binding protein C3 gene (MYBPC3), encoding for an adrenergic-responsive regulator of cardiac contractility and leading to hypertrophic cardiomyopathy, has been found to be upregulated in female WS breasts." (PMID 40841884, 2025). "Hypertrophic cardiomyopathy is often caused by pathogenic MYBPC3 variants." (PMID 39160446, 2025). "Despite decades of research studying MYBPC3’s roles in hypertrophic cardiomyopathy, much remains unknown about how pathogenic MYBPC3 variants cause disease." (PMID 41292636, 2025). "Hypertrophic cardiomyopathy is connected to mutations in the MYBPC3 gene that codes for cMyBP-C." (PMID 38741729, 2024). "Genes associated with Mendelian forms of hypertrophic cardiomyopathy (HCM) (MYBPC3, ALPK3 and FHOD3) were also identified at genomic risk loci for DCM, a finding consistent with evidence that these disorders represent opposing extremes of a continuum of ventricular structure and systolic function." (PMID 39572783, 2024). "In 2017, the first therapeutic germline intervention using CRISPR-Cas9 was reported, where researchers corrected the genetic defects of zygotes resulting from the microinjection of sperm with the MYBPC3 mutation, which predisposes the offspring to develop hypertrophic cardiomyopathy." (PMID 39201081, 2024). "Mutations in the gene encoding for cMyBP-C (MYBPC3) are the second most common cause of inheritable Hypertrophic Cardiomyopathy (HCM) in the human population, and knockout of cMyBP-C leads to the development of cardiomyopathies and heart failure in transgenic animal models." (PMID 36913580, 2023). "Notably, the mutation in the MYBPC3 gene, located in the exon 30 and known as the rs1052373, has been identified as a common cause of hypertrophic cardiomyopathy (HCM)." (PMID 37754829, 2023). "In the pediatric population, it has been reported that 14% of pediatric hypertrophic cardiomyopathy cases are caused by compound heterozygous variants in MYBPC3, which occur when both copies of a particular gene each carry a mutation (not necessarily the same mutation)." (PMID 36980931, 2023). "To date, this specific MYBPC3 c.1224-52 G>A (IVS13-52 G>A) variant has only been identified in adult patients with hypertrophic cardiomyopathy containing a heterozygous variant or unknown heterozygosity." (PMID 36980931, 2023). "This difference comes from a difference in the cell cycle, accelerated in Mybpc3 and delayed in Lmna mutant mice, and presumably contributes to the phenotypic divergence of developing hypertrophic cardiomyopathy in patients with MYBPC3 mutation while developing DCM in those with LMNA mutation." (PMID 34250035, 2021). "MYBPC1 appears to be a novel gene responsible for DA1, though the mechanism of disease may differ from how some cardiac MYBPC3 mutations cause hypertrophic cardiomyopathy." (PMID 34356068, 2021). "A MYBPC3 mutation was noted in patients with inherited hypertrophic cardiomyopathy." (PMID 33036415, 2020). "Additionally, we evaluated the effect of cryopreservation on cardiomyocytes generated from two hiPSC lines derived from hypertrophic cardiomyopathy (HCM) patients carrying a mutation in myosin binding protein C3." (PMID 31945612, 2020).